CCR2 (C-C motif chemokine receptor 2)
Diseases named in the same sentence as CCR2 in open-access papers (continued):
Sharing a sentence is not in itself a finding about the gene and the disease.
Cognitive impairment (24 papers, 2014 to 2025). Abnormal cognition is characterized by deficits in thinking, reasoning, or remembering. "The processes involved in neuroinflammation during hypertension are complex and our findings suggest that blood-brain barrier breakdown and CCR2 expression are likely to be involved, and this was associated with the development of cognitive impairment." (PMID 40697973, 2025). "The effects of long non-coding (lnc) RNA-PTENP1 mRNA and chemokine receptor-2 (CCR2) polymorphisms on cognitive impairment in HGG patients was investigated by Yang and colleagues." (PMID 37047356, 2023). "Similar to what is observed in rodents after TBI CCR2 deficiency prevents neuronal dysfunction and cognitive deficits after exposure to therapeutic brain irradiation and radiation and TBI combined injury." (PMID 36142198, 2022). "Using CCR2 knockout mice, they showed that CCR2 deficiency prevented cranial irradiation-induced neuronal damage and cognitive impairment." (PMID 28529513, 2017). "The CD14 + CD16+ monocytes that crossed an artificial blood–brain-barrier model as well as those found in the CSF of individuals with HIV-associated cognitive impairment, were found to preferentially express CCR2." (PMID 25852823, 2015). "It was found that the rs7853346 polymorphism in lncRNA-PTENP1 and the rs1799864 polymorphism in CCR2 may influence cognitive impairment much more if they are present concomitantly." (PMID 37047356, 2023). "Similarly, cognitive impairments caused by cranial irradiation in mice were prevented by a CCR2 knockdown, which suggests that this receptor is a mediator of neuronal damage following injury and inflammation." (PMID 31829243, 2019). "Treatment with anti-CCR2 monoclonal antibodies (mAbs) blocked the entry of CCR2+ monocytes into the brain and thus protected the brain from cognitive impairment." (PMID 36445634, 2023). "When performing site-directed pre-injection on rats with RS504393, a CCR2 antagonist, the drug abrogated surgery-induced cognitive deficits and abolished pro-inflammatory microglial polarization and subsequent neuronal loss." (PMID 36503642, 2022). "In our subsequent study, we examined the effects of aging on the crosstalk between sub-chronic response to TBI of peripherally-derived monocytes (CD45hi; CCR2+) and the onset of chronic cognitive deficits." (PMID 36142198, 2022). "Altogether, we advanced a macrophage-directed therapy that effectively blocked CCR2 and attenuated TBI-induced inflammation, coincident with amelioration of hippocampus-associated cognitive deficits." (PMID 36142198, 2022). "In the current study, we investigated the impact of age on the subchronic response of peripherally-derived monocytes (CD45hi; CCR2+) and their role in the development of chronic cognitive deficits." (PMID 29848996, 2018). "A very recent set of studies suggests a mechanism for CCR2/CCL2 signaling in the recruitment and trafficking of CD14 + CD16+ monocytes into the brain in HIV-associated cognitive impairment." (PMID 25852823, 2015). "Recent studies identified the chemokine (C-C motif) receptor (CCR2), constitutively expressed by cells of the monocyte-macrophage lineage, as a mediator of cognitive impairments induced by irradiation." (PMID 24695541, 2014). "On one hand, CCR2-expressing macrophages were accumulated in hippocampi of mice undergoing experimental surgeries, and upregulation of CCL2 in activated astrocytes and elevated CCR2 expression in activated microglia induced cognitive deficits in a tibial-fracture-surgical model." (PMID 36503642, 2022). "Similarly, CCR2 deficiency in bone marrow cells in APP/PS1 mice also led to aggravation of cognitive impairment and increased levels of soluble Aβ oligomers, pointing to the role of bone marrow-derived CCR2-positive microglia in phagocytosis of soluble Aβ." (PMID 35821178, 2022). "Similar to EA, CCR2 deficiency, L-158,809, and ramipril prevent cognitive impairments, but do not influence neurogenesis." (PMID 25830357, 2015).
Cognitive impairment (continued). "Furthermore, oral cannabinoids also significantly increased CCR2-expressing non-classical monocytes, a loss of this subpopulation had been associated with cognitive impairment in PWH not taking ART." (PMID 37508476, 2023). "We and others have shown that radiation induces infiltration of peripheral myeloid cells that depend on CCR2 signaling and that loss of the cytokine receptor CCR2 prevented the development of radiation-induced long-term cognitive deficits with no influence on neurogenesis." (PMID 27576527, 2016). "Our findings highlight a neuroprotective role for CCR2 in limiting CD8 T cell-mediated neuroinflammation and cognitive deficits, providing insights into potential therapeutic targets for CNS infections." (PMID 39345540, 2024). "More specifically, our group demonstrated that peripherally-derived macrophages (CCR2+) propagate to the injured brain and participate in chronic TBI-induced cognitive deficits in young animals." (PMID 36142198, 2022). "We previously showed that inhibiting the infiltration of peripherally-derived monocytes via CCR2 signaling prevented the development of chronic, TBI-induced cognitive deficits in young mice." (PMID 29848996, 2018). "We previously established that peripherally-derived monocytes (CCR2+) infiltrate the injured brain and contribute to chronic TBI-induced cognitive deficits in young animals." (PMID 29848996, 2018). "Also, with the use of a selective antagonist for CCR2 (the CCL2 receptor) in a traumatic brain injury model, accumulation of macrophages in the hippocampus was reduced as were cognitive impairment and inflammation." (PMID 31829243, 2019).
HIV-1 infection (24 papers, 2010 to 2025). The type species of lentivirus and the etiologic agent of acquired immunodeficiency syndrome (AIDS). "CCR2 is one of the most extensively studied genetic factors confirmed to be linked to host resistance to HIV-1 infection." (PMID 39346778, 2024). "The CCR5/CCR2 gene cluster, which spans 20 kb on chromosome 3p21.31, has been found to be a highly diverse region with many phenotypic SNVs; thus, CCR5/CCR2 haplotypes are used for analysis of the association of candidate genes with HIV-1 infection." (PMID 37198402, 2023). "Third, considerable uncertainty remains about the functional relevance of the HHF*2 polymorphism and CCR2 itself to HIV-1 infection." (PMID 21429204, 2011). "The CCL2/CCR2 axis is linked to viral replication and immune activation during HIV-1 infection, and modulation of this axis may have an impact on HIV disease progression." (PMID 32626718, 2020). "The CCR5 promoter 59029 G/G genotype may be associated with the risk for HIV-1 infection in this population, while the CCR2-64I (A/A genotype) may account for the protection against HIV infection." (PMID 23880174, 2013). "We found that CCR2 was downregulated on the classical monocyte subsets but upregulated on the intermediate monocyte subsets during acute HIV-1 infection." (PMID 32626718, 2020). "CCR2-64I (A/A genotype) and SDF1-3'A are also known to protect against HIV infection, while CX3CR1 expression is associated with an increased risk of HIV-1 infection." (PMID 30998710, 2019). "Using this monocyte phenotyping panel we found that in untreated HIV-1 infection there is lower density of CCR2 on inflammatory monocytes and lower expression of CX3CR1 on patrolling monocytes." (PMID 26430882, 2015). "Polymorphisms of the genes for CCR5 (CCR5-Delta32), CCR2, and stromal-derived factor 1 (SDF1) have been found to modulate the susceptibility of individuals to HIV-1 infection and/or the pathogenic progression." (PMID 26300579, 2015). "The aim of this study was to assess HIV-2 susceptibility to cenicriviroc, a novel, once-daily, dual CCR5 and CCR2 antagonist that has completed Phase 2b development in HIV-1 infection." (PMID 26247470, 2015). "Polymorphisms in chemokine (C-C motif) receptors 2 and 5 genes (CCR2 and CCR5) have been associated with HIV-1 infection and disease progression." (PMID 21429204, 2011). "Contrary to what was observed in our study, a meta-analysis based on published studies on CCR2-64I regarding susceptibility to HIV infection concluded that this allele does not affect the risk of HIV-1 infection." (PMID 40413451, 2025). "Thus, individuals in various populations harboring CCR2-64I, CCR5Δ32, and CCR5 promoter A/G mutations are less susceptible to HIV-1 infection and progress much more slowly to AIDS." (PMID 39346778, 2024). "The CCL2/CCR2 axis plays a critical role in the pathogenesis of HIV-1 infection." (PMID 38005838, 2023). "For instance, CCR2-V64I (rs1799864) has an association with certain SNPs (e.g., rs1799987) in the CCR5 cis-regulatory region and plays a beneficial role during HIV-1 infection." (PMID 37198402, 2023). "The CCR2 allele is a prominent receptor for the monocyte chemoattractant protein (MCP) group of C–C chemokines and is among the most important genetic factors known to be associated with host resistance to HIV-1 infection." (PMID 26300579, 2015). "Notably, polymorphisms of the genes for CCR5, CCR2 and stromal-derived factor 1 (SDF1) have been found to modulate the susceptibility of individuals to HIV-1 infection and/or the pathogenic progression." (PMID 23880174, 2013). "This suggests that the CCR2-64I allele is unlikely to be associated with the low prevalence of HIV-1 infection in our population." (PMID 23880174, 2013). "The CCR5-∆32 and CCR2-64I alleles have been shown to have a strong protective effect on progression of HIV-1 infection, but SDF1-3′A homozygosity carried no such protection." (PMID 23880174, 2013).
HIV-1 infection (continued). "Genomic scan analyses have suggested that the chemokine receptor cluster (CCR2, CCR3, CCR5 <300 kb span) on the short arm of chromosome 3 may contribute to susceptibility to HIV-1 infection and to the expression of a number of inflammatory diseases." (PMID 20220260, 2010). "Similarly, in a Chinese cohort, the CCR2 A allele was not protective against the acquisition of HIV-1 infection, but this variant was shown to influence the clinical category, with a predominance of symptomatic infections." (PMID 35407496, 2022). "Therefore, investigating the allelic variations of important genetic polymorphisms, such as CCR5-Delta32, CCR2-64I, and SDF1-3′A, as well as their distribution across populations, may provide crucial insights into the HIV-1 infection epidemiology, disease progression, and its clinical management." (PMID 40413451, 2025). "HIV-1 infection upregulates expression of both CCL2 and its receptor CCR2, and high levels of CCL2/CCR2 are observed in HIV-1-infected patients." (PMID 38005838, 2023). "So far, the role of CCR2 expression on CD8+ T cells, especially in HIV-1 infection, remains mostly elusive." (PMID 33659876, 2021). "Ackr3, Pld1, and Ccr2 expression up-regulation had patterns very similar to Ccr5 and further indicate that AMPH and EIH can exacerbate HIV-1 infection." (PMID 30779732, 2019). "In particular, CCL2, mainly produced by monocytes/macrophages both in vitro and in vivo, recruits CCR2+CD4+ T lymphocytes and monocytes/macrophages, which represent key target cells for HIV-1 infection." (PMID 25608886, 2015). "The CCR2 chemokine receptor (also termed CKR2; CCR2A; CCR2B; CD192; MCP-1-R; CC-CKR-2) is an alternative co-receptor for HIV-1 infection that is only used by a few strains." (PMID 24167505, 2013). "The major published studies examining the effects of CCR2 and CCR5 SNPs/haplotypes/diplotypes on HIV-1 infection or disease progression have shown a wide spectrum of effects in various populations." (PMID 21429204, 2011). "In summary, we have identified distinct perturbations in circulating monocyte phenotypes in patients with untreated HIV-1 infection: elevated expression of HLA-DR and CD86 that normalized with ART while expression of the chemokine receptors CX3CR1 and CCR2 rose with ART." (PMID 26430882, 2015). "So far, similar suppression of both X4 and R5 HIV-1 infection has also been reported in a study utilizing anti-human CCR2 mAb that is neither agonistic nor antagonistic." (PMID 22018245, 2011). "A genetic variant of CCR2 (CCR2-V64I) leads to variations in the CCR2 transmembrane region and has been associated with slow progression to AIDS; however, its effect on susceptibility to acquire HIV-1 infection has not been defined to date." (PMID 25202468, 2014).
osteoarthritis (24 papers, 2015 to 2025). A noninflammatory degenerative joint disease occurring chiefly in older persons, characterized by degeneration of the articular cartilage, hypertrophy of bone at the margins and changes in the synovial membrane. "CCR2+ macrophages were abundant in human osteoarthritis synovium and associated with cartilage erosion." (PMID 40860192, 2025). "C–C chemokine receptor 2 (CCR2) signaling plays a key role in pain associated with experimental murine osteoarthritis (OA) after destabilization of the medial meniscus (DMM)." (PMID 33827672, 2021). "Strikingly, monocytes are also involved in osteoarthritis, as monocyte recruitment causes cartilage destruction mediated by CCL2/CCR2 in experimental osteoarthritis." (PMID 40067374, 2025). "Osteoarthritis (OA) is characterized by a complex interplay of molecular signals orchestrated by the CCL2/CCR2 axis." (PMID 39076996, 2024). "CCL2 is particularly relevant in the context of osteoarthritis development following IAF as the CCL2/CCR2 signaling axis is a potent mediator both pain and macrophage chemotaxis into the injured tissue." (PMID 37400744, 2023). "For instance, CCR2 participates in chondrocyte degradation and leads to the progression of osteoarthritis." (PMID 34488536, 2021). "It was reported that monocytes recruited via CCL2/CCR2, were related to immune activation and inflammation to propagate inflammation and tissue damage in osteoarthritis (OA)." (PMID 32626718, 2020). "CCR2 has also been explored as a target in osteoarthritis (OA)." (PMID 33827672, 2021). "CCL2, a ligand for CCR2, is an inflammatory chemokine that is highly present in the serum of patients with RA relative to the serum of those with osteoarthritis, and a positive correlation has been reported between serum CCR2 concentration and RA disease activity." (PMID 27267914, 2016). "MCP-1 is one of the chemokines which is involved in osteoarthritis, the ligand is CCR2." (PMID 26578310, 2015). "CCR2, GPR4, α2A-AR, and CaSR will accelerate the progression of osteoarthritis." (PMID 40860192, 2025). "Monocytes recruited via Ccl2/Ccr2, rather than Ccl5/Ccr5, propagate inflammation and tissue damage in osteoarthritis, thereby representing a promising therapeutic approach." (PMID 34917083, 2021). "Interestingly, another study found that mice lacking C-C motif chemokine ligand 2 (CCL2) or C-C motif chemokine receptor 2 (CCR2), but not CCL5 or CCR5, were protected against osteoarthritis with reduced monocyte/macrophage recruitment." (PMID 40860192, 2025). "Targeting of CCL2 and CCR2 might be a potential treatment of osteoarthritis (OA); in vivo findings from a murine OA model indicated that selective targeting of CCL2/CCR2, rather than CCL5/CCR5, was a viable therapeutic strategy." (PMID 37457301, 2023). "At the same time, their studies showed that the level of CCL2 in the synovial fluid of OA patients was significantly higher than that of ordinary people (CCL2/CCR2, but not CCL5/CCR5, mediates monocyte recruitment, and utilization destruction in osteoarthritis)." (PMID 36619785, 2022).
type 2 diabetes (24 papers, 2007 to 2026). "Accumulating studies in mice have demonstrated that CCR2 selective inhibitors or CCR2/5 inhibitors can significantly improve type 2 diabetes." (PMID 35757707, 2022). "Pharmacological blockade of CCL2 or CCR2 have successfully entered clinical trials studying treatment of type 2 diabetes and nephropathy." (PMID 35699239, 2022). "For example, CCR2 antagonists were used in the treatment of type 2 diabetes in a phase I clinical trial." (PMID 35874713, 2022). "A previous randomized trial involving patients with type 2 diabetes reported that administration of a CCR2 antagonist, JNJ‐41443532, resulted in decreased levels of weighted‐mean and fasting plasma glucose over 28 days of treatment." (PMID 32704573, 2020). "Our previous study has demonstrated that the function and structure of kidney could be improved by CCR2 inhibitor treatment in type 2 diabetic mice model." (PMID 31498850, 2019). "CCR2+ monocytes and adipose tissue macrophages activated to a pro-inflammatory M1-like phenotype play critical roles in onset and progression of type 2 diabetes and associated complications by sustaining non-resolving inflammation and insulin resistance." (PMID 28993702, 2017). "In addition, two kinds of CCR2 antagonism, rs504393 and ro5234444, could block the development of DN by decreasing macrophage infiltration of the kidney in type 2 diabetes mice." (PMID 36969169, 2023). "On the basis of these biological effects, this pilot study assessed the feasibility and potential efficacy of CCR2 inhibition by PG in terms of albuminuria as well as HbA1c and CRP levels in patients with type 2 diabetes and nephropathy." (PMID 32704573, 2020). "Various other CCR2, CCL2, or CCR2/CCR5 inhibitors are currently developed and tested in other inflammatory/metabolic diseases (e.g., type 2 diabetes), clinical trials are needed though to define their efficacy in liver diseases." (PMID 30619308, 2018). "Recently, in a randomized controlled clinical trial the effect of the CCR2 antagonist, JNJ-41443532, was examined in obese patients with type 2 diabetes." (PMID 28076416, 2017). "Unlike the WT mice, the infected CCR2−/− mice did not develop severe neurological and behavioral defects, as quantified per murine coma and behavior scale (MCBS)." (PMID 34311579, 2021). "We tested association of nine single nucleotide polymorphisms (SNPs) from TGFβ1, TNFα, CCR2 and CCR5 genes among individuals with type-2 diabetes with and without renal insufficiency." (PMID 17428349, 2007). "However a CCR2 antagonist (CCX140-B) shows therapeutic effect on type II diabetes in a phase II trial without affecting the blood monocyte count, suggesting that targeting CCR2 could remain as an important therapeutic strategy for metastatic cancer." (PMID 26275794, 2015). "Another trial involving patients with type 2 diabetes and nephropathy reported that changes in HbA1c, fasting plasma insulin and HOMA‐IR in response to a CCR2 inhibitor, CCX140‐B, were not significant compared with the response to the placebo." (PMID 32704573, 2020).